CCND1 (cyclin D1)
Diseases named in the same sentence as CCND1 in open-access papers (continued):
Sharing a sentence is not in itself a finding about the gene and the disease.
acral melanoma (21 papers, 2014 to 2025). "Tumours in this subgroup displayed many somatic SVs and amplifications of CCND1, a common alteration in acral melanomas associating with ulceration and localized metastasis." (PMID 37420249, 2023). "Identified CNVs in acral melanoma have implicated several genes, including CCND1, CDK4, hTERT, PAK1, GAB2, EP300, YAP1, and MDM2." (PMID 35997352, 2022). "In our cohort we found that CCND1 copy number increase was associated with the Breslow thickness in invasive acral melanomas." (PMID 34225728, 2021). "CCND1 copy number increase is associated with the Breslow thickness (P = 0.043) in invasive acral melanomas." (PMID 34225728, 2021). "Cdk4 gain, Ccnd1 gain and the combination of Cdk4 gain and Ccnd1 gain were associated with the poor prognosis of acral melanoma, respectively." (PMID 31358010, 2019). "Increase in CCND1 copy number was associated with Breslow thickness in invasive acral melanoma." (PMID 34225728, 2021). "Cyclin D1 (CCND1) and CDK4 copy number gains often appear in acral melanoma, suggesting a pathogenic role." (PMID 40282469, 2025). "By contrast, acral melanomas are more often driven by high amplitude amplifications of CCND1, CDK4, MDM2, and TERT, among other genes." (PMID 39034322, 2024). "The only mucosal melanoma in the data harboured a CCND1 amplification and clustered with the acral melanomas." (PMID 37420249, 2023). "Regarding the cell cycle pathway, CDK4/CCND1 amplifications were more common in NAM and CDKN2A/B loss occurred mostly in acral melanoma." (PMID 36983205, 2023). "When it comes to acral melanoma, cyclin D1 has been reported to be overexpressed, resulting in constitutively activated MAPK signaling pathway without NRAS or BRAF mutations." (PMID 35484605, 2022). "The earliest genetic alteration in acral melanoma is the amplification of CCND1, which is detected in the very early stages of acral melanoma in situ." (PMID 35997352, 2022). "BRAF and NRAS mutations are common in acral melanocytic nevus, whereas acral melanoma shows lower rates of KIT, NF1, BRAF, and NRAS mutations and remarkable copy number variations in genes such as CCND1, CDK4, hTERT, PAK1, and GAB2." (PMID 35997352, 2022). "In a multi-fluorescence in situ hybridization study, the frequency of CCND1 amplification in 44 Chinese patients with acral melanoma was 45.4%." (PMID 34149718, 2021). "Abnormalities of the CCND1 gene are found in some malignant melanocytic tumors, and especially in acral melanoma." (PMID 34225728, 2021). "In acral melanomas with high-level CCND1 copy number increase, the median IHC score was 60% (range: 1–95%)." (PMID 34225728, 2021). "High-level increase in the CCND1 copy number can induce high cyclin D1 protein expression in acral melanomas." (PMID 34225728, 2021). "In acral melanoma, most CCND1 abnormalities are characterized by an increase of the gene copy number, and CCND1 copy number changes are not found in acral melanocytic nevi." (PMID 34225728, 2021). "Our results show high-level CCND1 copy number increase has good correlation with cyclin D1 protein expression in acral melanoma." (PMID 34225728, 2021). "CCND1 copy number increase is characteristic of acral melanoma and is useful in distinguishing benign and malignant acral melanocytic lesions." (PMID 34225728, 2021). "Specifically, the mean CCND1 copy number per cell and percentage of cells with CCND1 amplification were considerably higher in the acral melanoma group, with the average of 3.74–3.03 (p = .073) and 76.74–58.67% (p = .007), respectively." (PMID 32393283, 2020). "Studies have indicated frequent amplification of genes involved in the CDK4 pathway including CCND1 in acral melanoma, indicating the potential for CDK4/6 inhibitors." (PMID 32393283, 2020). "Conversely, mucosal and acral melanomas frequently harbour mutations and/or amplifications of KIT, often associated with cyclin D1 (CCND1) or cyclin-dependent kinase 4 (CDK4) amplifications, but very rarely contain BRAF mutations." (PMID 31581559, 2019).
acral melanoma (continued). "Additionally, CCND1 amplification and CDKN2A loss—which are common genetic alterations seen in acral melanoma—can activate the CDK4 pathway, promoting primary resistance to therapy." (PMID 41010951, 2025). "Melanoblasts with CCND1 amplification were detected in the secretory portion of eccrine glands among human melanoma cells, suggesting that these cells could give rise to acral melanomas." (PMID 39202970, 2024). "Cyclin D1 IHC cannot serve as a surrogate for CCND1 FISH in acral melanomas." (PMID 34225728, 2021). "However, for acral melanoma with low-level CCND1 copy number increase, copy number increase is most likely merely a result of genetic instability which occurs during tumor progression and does not induce increase in protein expression." (PMID 34225728, 2021). "We wished to determine whether increases in CCND1 gene copy number and cyclin D1 protein expression is correlated in acral melanoma." (PMID 34225728, 2021). "That is, when invasive acral melanoma shows CCND1 copy number increase the tumor will be thicker." (PMID 34225728, 2021). "Twenty-nine acral melanomas (47.5%, 29/61) showed increased CCND1 copy number." (PMID 34225728, 2021). "In addition, genetic alterations in CDK4 pathway components (CDK4, CCND1, and CDKN2A), which are particularly common in Asians, have been associated with innate resistance to PD-1 blockade in patients with acral melanoma." (PMID 34149718, 2021). "However, the significance of CCND1 gain in the occurrence or in situ state of acral melanoma needs further studies." (PMID 32393283, 2020). "Additionally, acral melanomas frequently harbor copy number gains in CCND1 and CDK4 and losses of CDKN2A, and a large preclinical study showed that palbociclib monotherapy was effective in treating acral melanoma patient derived xenograft tumors with various alterations to Cyclin–CDK circuitry." (PMID 40282469, 2025). "In addition, acral melanoma frequently exhibits complex structural alterations, including amplifications and deletions of chromosomes, particularly affecting the cyclin D1 (CCND1), cyclin-dependent kinase 4 (CDK4), and telomerase reverse transcriptase (TERT) genes." (PMID 39202970, 2024). "Therefore, CCND1 focal amplification could be considered as a potential driver in the context of chromothripsis in acral melanomas." (PMID 33804108, 2021). "At this time we do not know the exact mechanism of high cyclin D1 expression in absence of an increased CCND1 copy number in acral melanoma." (PMID 34225728, 2021). "In acral melanomas with no CCND1 copy number alteration, the median IHC score was 15% (range: 1–80%)." (PMID 34225728, 2021). "Thirty-two acral melanomas (52.5%, 32/61) showed no CCND1 copy number alterations." (PMID 34225728, 2021).
colorectal tumors (21 papers, 2007 to 2025). "More importantly, we found that decreased MG53 was associated with upregulation of cyclin D1 in colorectal tumors from patients, and the amount of these two proteins were negatively correlated." (PMID 37414783, 2023). "Consistent with whole-body Nlrp12-KO mice, intestinal epithelial cell–specific Nlrp12-KO mice showed higher activation of β-catenin and expression of its downstream target cMyc and cyclin D1 in colorectal tumors." (PMID 37581937, 2023). "Persistent activation of STAT3 and cyclin D1 overexpression also contribute to enhanced cellular proliferation in colorectal tumor growth." (PMID 32024285, 2020). "To confirm further the results of the in vitro experiments, we used immunofluorescence to detect the expression of P-STAT 3, IL-6, Bcl-2, and Cyclin D1 in colorectal tumors." (PMID 33082817, 2020). "For instance, a strong correlation was reported between β-catenin deregulation and cyclin D1 expression in primary colorectal tumors." (PMID 27252679, 2016). "Cyclin D1 overexpressed has been reported to occur in 40-70% of colorectal tumors." (PMID 28938543, 2017). "Cyclin D1 overexpression has been reported to occur in 40–70% of colorectal tumors." (PMID 24728073, 2014). "Moreover, it has been observed that ursolic acid may potentially enhance the radiosensitivity of human colorectal tumor cells through the NF-κB1 and CCND1 signaling pathways." (PMID 37833759, 2023). "In addition, Pin1 overexpression might be attributable to stabilization of β-catenin and cyclin D1 in human colorectal tumor-initiating cells." (PMID 35433695, 2022).
laryngeal squamous cell carcinoma (20 papers, 2004 to 2024). A squamous cell carcinoma that arises from the larynx. "circ‐CCND1 was found to be markedly up‐regulated in laryngeal squamous cell carcinoma (LSCC) and closely associated with aggressive clinical features and adverse prognosis." (PMID 31951319, 2020). "For example, the overexpression of CCND1 promoted cell proliferation of laryngeal squamous cell carcinoma." (PMID 36612120, 2022). "The complex between circ-CCND1 and ELAVL1 promotes the expression of the gene encoding cyclin D1 and ultimately leads to the malignant proliferation of laryngeal squamous cell carcinoma." (PMID 35465324, 2022). "A previous study demonstrated that circCCND1 interacted with HuR protein to elevate the expression of CCND1, thus promoting the proliferation of laryngeal squamous cell carcinoma cells." (PMID 34020639, 2021). "In laryngeal squamous cell carcinoma, circMYLK can facilitate cell proliferation by modulating the microRNA‐195/cyclin D1 axis." (PMID 32342645, 2020). "Notch1 knockdown in a laryngeal squamous cell carcinoma cell led to reduced Cyclin D1 and Cyclin E expression." (PMID 28860516, 2017). "The aim of this study was to study the expression of angiopoietin-2 (Ang-2) and the cell cycle protein D1 (cyclin D1) in laryngeal squamous cell carcinoma (SCC), and its clinicopathological meaning." (PMID 24223635, 2013). "Additionally, miR-195 was found to increase cyclin D1 (CCND1) expression in laryngeal squamous cell carcinoma." (PMID 38190139, 2024). "Circ-CCND1 and its host gene CCND1 (cyclin D1) were found to be highly expressed in laryngeal squamous cell carcinoma and could promote tumor cells proliferation and metastasis." (PMID 36091137, 2022). "Several studies have shown that cyclin D1 expression could be negatively regulated by miR-195 to affect the tumorigenicity and invasiveness of laryngeal squamous cell carcinoma and glioblastoma cells." (PMID 34271919, 2021). "Concerning laryngeal squamous cell carcinoma (LSCC), cyclin D1 oncogenic transformation leads to an aberrant protein expression and seems to affect the biological behaviour of the neoplasm." (PMID 32102514, 2020). "Therefore, circ-CCND1 promotes the tumorigenesis of laryngeal squamous cell carcinoma (LSCC) by increasing mRNA stability and expression of CCND1 at the post-transcriptional." (PMID 37060016, 2023).
endometriosis (19 papers, 2012 to 2024). The growth of functional endometrial tissue in anatomic sites outside the uterine body. "After knocking out the CCND1 mRNA, the proliferation of endometriosis cell lines is attenuated, the sub-G0/G1 cell cycle is stopped, and apoptosis is increased." (PMID 38397379, 2024). "Cyclin D1 expression was shown to be higher in the secretory phase stromal cells of patients with endometriosis than in the secretory phase stromal cells of healthy women." (PMID 35059465, 2022). "We observed cyclin D1 levels deregulated in endometriosis cell line which was significantly elevated (5.4 folds) in E-MenSCs (P < 0.01) compared with NE-MenSCs." (PMID 35059465, 2022). "Cell proliferation and Cyclin D1 mRNA expression in epithelial and stromal cells of patients with endometriosis were effectively decreased by treatment with PKF 115–584, a small-molecule antagonist of the Tcf/β-catenin complex." (PMID 26056600, 2014). "Treatment with PKF 115–584 effectively decreased cell proliferation and Cyclin D1 expression in endometrial epithelial and stromal cells of patients with endometriosis." (PMID 23626717, 2013). "Consequently, it was observed that in endometrial epithelial cells from patients with endometriosis, Cyclin D1, a Tcf/β-catenin target gene, had significantly higher mRNA expression in the mid-secretory phase." (PMID 38398530, 2024). "While let-7 down-regulation has been associated with elevated KRAS levels, an inverse relationship between let-7b expression and the estrogen-regulated gene cyclin D1 has also been documented as a possible mechanism for regulating cell proliferation in endometriosis." (PMID 34449536, 2021). "With the development of more effective and less toxic agents, cyclin D1 inhibitors could be used clinically for treating endometriosis in the future." (PMID 28720098, 2017). "Furthermore, regulation of cyclin D1, one of the target genes of the Wnt pathway via activation of β-catenin, is impaired in endometrial stromal cells of patients with endometriosis." (PMID 26056600, 2014). "According to previous studies, there is an increased expression of cyclin D1 and matrix metalloproteinase (MMP) 9 in the ESCs of patients with endometriosis." (PMID 34531822, 2021). "Functional analysis indicated that 673 miRNA targets constitute molecular pathways involved in the development of endometriosis, including c-Jun, CREB-binding protein, protein kinase B (Akt), and cyclin D1 (CCND1) signaling." (PMID 24927773, 2014). "For example, compared with MSCs in women without endometriosis (normal MSCs), MSCs in endometriosis patients (endometriotic MSCs) express higher levels of Cyclin D1, Matrix metalloproteinases (MMP)-2, and MMP-9." (PMID 36358904, 2022). "This study aimed to determine whether arcyriaflavin A, a representative inhibitor of cyclin D1–cyclin-dependent kinase 4 (CDK4), is beneficial in the treatment of endometriosis." (PMID 28720098, 2017). "Expression levels of Cyclin D1 tended to be higher in the secretory phase stromal cells of patients with endometriosis compared to patients without endometriosis, which is in agreement with with the results of a previous study." (PMID 26056600, 2014). "Some literatures documented that expression of endometriosis-related genes; cyclin D1, cyp19 and cox-2 depend on non-genomic ERK pathway." (PMID 23029074, 2012). "We hypothesized that cyclin D1 and CDK inhibitors might alleviat endometriosis." (PMID 28720098, 2017). "In addition, mRNA expression of Cyclin D1, a Tcf/β-catenin target gene, was significantly higher in endometrial epithelial cells of patients with endometriosis compared to patients without endometriosis in the mid-secretory phase." (PMID 26056600, 2014). "Western blot analysis revealed that Cyclin D1 protein expression levels in non-treated epithelial cells prepared from the mid-secretory and menstrual phases were significantly higher in patients with endometriosis than in patients without endometriosis." (PMID 23626717, 2013).
endometriosis (continued). "In addition, the present results demonstrated significantly higher expression of Cyclin D1, a Tcf/ß-catenin target gene, in endometrial epithelial cells of patients with endometriosis compared to patients without endometriosis in the mid-secretory phase." (PMID 23626717, 2013). "Cyclin D1 mRNA expression levels in non-treated epithelial cells prepared from the mid-secretory and menstrual phases were significantly higher in patients with endometriosis than in patients without endometriosis." (PMID 23626717, 2013). "Moreover, miR-20a targets E2F transcription factor 3 (E2F3) and Cyclin D1 (CCND1), and thus participates in epithelial cell proliferation and decreased apoptosis (antiapoptotic action); it also targets interleukin-8 (IL-8) and TGF-β, which promotes epithelial–mesenchymal transition in endometriosis." (PMID 34449536, 2021). "Therefore, cyclin D1 and MMP9 may be potential targets for endometriosis." (PMID 34531822, 2021).
medulloblastoma (19 papers, 2009 to 2025). A malignant, invasive embryonal neoplasm arising from the cerebellum. "An association between CTNNB1 nuclear staining and CCND1 overexpression in the primary medulloblastomas just below significance was identified (Fisher's Exact Test, P=0.052)." (PMID 19293793, 2009). "Ginkgetin treatment led to the downregulation of cyclin D1 in prostate cancer cells, osteosarcoma cells, and medulloblastoma cells." (PMID 40762894, 2025). "RNF220 mediates medulloblastoma development by epigenetic modulation of Shh signal pathway, as well as accelerates the leukemic cells proliferation and declines the Cyclin D1 protein degradation." (PMID 34753387, 2021). "In medulloblastoma, CCND1 overexpression (nuclear) was seen in 4 out of 37 (11%) primary tumours with percentages of positive cells ranging from 14 to 22%." (PMID 19293793, 2009). "In mouse models with constitutive Shh pathway activation, medulloblastoma tumorigenesis shows several stages of progression, with clusters of preneoplastic GNPs (pGNPs) that actively express Shh target genes such as cyclin D1 remaining on the surface of the mature cerebellum." (PMID 29234490, 2017). "MiR-193a not only targeted MAX but several proliferation-related genes like CCND1, E2F1, STMN1, and chromatin modifier gene KMT2A that brought about widespread repression of gene expression in the MYC amplified Group 3 medulloblastoma cells." (PMID 32410663, 2020). "MiR-193a mediated decrease in the expression levels of known targets CCND1, MCL1, and the novel target MAX in the medulloblastoma cells was validated by the western blot analysis." (PMID 32410663, 2020). "The decrease in the expression levels of proliferation-related targets of miR-193a like E2F1, CCND1, and several other cell cycle regulators like CDK2, CCND2 is consistent with the growth inhibition of medulloblastoma cells upon the expression of miR-193a." (PMID 32410663, 2020). "In the analysis of a large group of pediatric embryonal brain tumors including medulloblastoma and supratentorial neuroectodermal tumor (sPNET), CDK6 and CCND1 gene amplification are more commonly observed in sPNET (25%)." (PMID 29416789, 2018). "Since siRNA-mediated depletion of the BRD2 BET protein has been described to reduce transcription of cyclin D1 in human cells, we investigated the result of siRNA-mediated BRD4 knockdown on CCND1 regulation in medulloblastoma cells." (PMID 24231268, 2013). "The evidence, although significant, was not as strong in the medulloblastoma cohort, with 70% of tumours displaying nuclear localisation of CTNNB1 showing no CCND1 overexpression." (PMID 19293793, 2009). "The scorable and unscorable samples in the medulloblastoma cohort were very similar to the CTNNB1 and CCND1 analyses; therefore, no new comparison was made." (PMID 19293793, 2009).